MTOR (mechanistic target of rapamycin kinase)
Diseases named in the same sentence as MTOR in open-access papers (continued):
Sharing a sentence is not in itself a finding about the gene and the disease.
tumor (continued). "Furthermore, a subset of radioresistant stem‐like tumor cells characterized by their perivascular distribution appear to activate PI3K/Akt/mTOR signaling following irradiation, undergo brief cell‐cycle arrest and then gradually begin dividing again, presumably leading to disease recurrence." (PMID 19076778, 2009). "Interestingly, activation of the PI-3 kinase/Akt/mTOR pathway has been previously shown to suppress autophagy and direct apoptosis-resistant tumor cells under stress to necrotic cell death, which results in inflammation and accelerated tumor growth." (PMID 18335034, 2008). "Thus, mTOR blockade is pursued to interfere at multiple levels with tumour growth." (PMID 18319715, 2008). "In addition, targeting together mTOR and EGFR might cause a more profound effect on tumour growth control compared with a single agent." (PMID 18319715, 2008). "Therefore, identification of new molecular pathways such as PLD1/PA/mTOR signalling that are constitutively active in such types of tumours may be useful in selecting alternative targeted therapies." (PMID 17726467, 2007). "Central to TNBC pathobiology are the Akt/mTOR and MAPK/ERK signaling axes, both contribute to tumor progression and therapeutic resistance." (PMID 41799034, 2026). "Taken together, our data suggest that NPM1 is required for WNT-driven intestinal cell proliferation and tumor initiation; this dependency persists after oncogenic KRAS activation, which drives resistance to epidermal growth factor receptor and mTOR inhibition." (PMID 41413654, 2026). "Concurrently, EVI1 promotes cell survival and proliferation by modulating critical signaling pathways, including the potent inhibition of the tumor-suppressive TGF-β pathway and the activation of the pro-survival PI3K/AKT/mTOR cascade via PTEN suppression." (PMID 41777888, 2026). "In conclusion, miR-6850-5p and miR-6850-3p act as potent tumor suppressors in HGSOC by modulating cell proliferation, migration, adhesion, EMT, and the PI3K/Akt/mTOR pathway." (PMID 41282576, 2026). "Chronic inflammation, mediated by key signaling pathways including NF-κB, JAK/STAT, and PI3K/Akt/mTOR, dynamically remodels the cellular composition and function of the OCME, driving immune suppression, stromal remodeling, and tumor metastasis." (PMID 41601649, 2026). "These frequently happen via regulating important pathway signals, like PI3K/AKT/mTOR and NRF2, or by processes like miRNA sponging, creating a tumor microenvironment that is immunosuppressive and metabolically friendly." (PMID 41596634, 2026). "By modulating the PI3K/AKT/mTOR signaling axis and the pro-angiogenic microenvironment, ADGRD1 facilitates tumor growth and neovascularization." (PMID 42294320, 2026). "These drivers activate signaling pathways such as MAPK, PI3K/Akt/mTOR, STAT, and NF‐kB to induce cellular proliferation, anti‐apoptosis, metabolic reprogramming, EMT, tumor‐promoting inflammation, immune destruction, angiogenesis, and tumor invasion." (PMID 41450167, 2026). "The mTOR and PI3K‐Akt signaling pathways were closely related to cell proliferation and tumor angiogenesis." (PMID 41536518, 2026). "The TME plays a major role in tumor progression, metastasis, and resistance to conventional therapies through a network of dysregulated signaling pathways, including KRAS, PI3K/AKT/mTOR, Raf/MAPK/ERK, TGF-β, NF-κB, Notch and Hedgehog." (PMID 42294061, 2026). "Mechanistically, RAD18 promoted tumor proliferation, migration and immunosuppressive microenvironment remodeling by activating the AKT/mTOR/c-Myc axis and regulating TGF-β1/PD-L1 expression." (PMID 42115304, 2026). "BCc1 exhibits a dual regulatory effect—upregulating tumor-suppressive Beclin-1 while downregulating pro-survival ATG-4B, ATG-7, and mTOR—in a manner dependent on dose and administration route." (PMID 41550506, 2026). "In tumor cells, signaling pathways such as PI3K/AKT/mTOR, JAK/STAT3, and TGF-β/Smad form a robust defense system." (PMID 41599293, 2026).
tumor (continued). "Dysregulated kinase signaling particularly involving EGFR, PI3K/AKT/mTOR, MAPK, and ALK pathways drives tumor growth, survival, and metastasis." (PMID 41821616, 2026). "In summary, the mTOR pathway is activated by FGF19, which drives metabolic reprogramming in tumor cells and supports their growth and proliferation." (PMID 41328353, 2026). "In parallel, cannabinoids modulate the AMPK/mTOR axis, in which AMPK acts as a cellular energy sensor and suppresses mTOR signaling, leading to reduced tumor cell proliferation and enhanced autophagy." (PMID 41516397, 2026). "Simultaneously, selenium impairs tumor growth by halting the cell cycle and suppressing proliferative signals via PI3K/Akt/mTOR and MAPK pathways." (PMID 41496977, 2026). "Our study sought to delineate the molecular underpinnings of BCc1's anti-tumor effects in a BALB/c murine model of BC, focusing on key autophagy regulators (Beclin-1, ATG-4B, ATG-7) and the mTOR signaling axis." (PMID 41550506, 2026). "Metformin administered during early fibrosis prevented macroscopic tumor formation and suppressed PI3K/AKT/mTOR signaling." (PMID 41718347, 2026). "ARL4C promotes tumor survival and migration through the RAP1/PI3K-Akt/mTOR signaling loop and the RAC1/EMT signaling axis, and sustains its expression via deubiquitinase-mediated stabilization, thereby forming a positive feedback loop." (PMID 41328352, 2026). "Aberrant expression of hsa-miR-486-5p was found to modulate pathways including PI3K/AKT/mTOR, NF-κB, and JAK-STAT3, thereby promoting tumor progression and secretion of inflammatory cytokines." (PMID 42278237, 2026). "Research has shown that FKA possesses the ability to impede the growth of colon cancer cells, trigger programmed cell death in tumor cells, and hinder tumor-related signaling pathways such as PI3K/Akt and mTOR." (PMID 41599923, 2026). "10.13039/100014337Furthermore, RT-qPCR analysis showed a significant decrease in the mRNA expression of MTOR, CD44, and SAA1 in the combination group, further supporting the synergistic effect of PF-309 and OXA in inhibiting tumor growth." (PMID 41459112, 2026). "The regulation of mTOR/AMPK-dependent metabolic pathways and/or MCT1 lactate transporter activity protects DCs from the deleterious effects of tumor-derived metabolic byproducts, thus enabling robust anti-tumor immune responses." (PMID 41601626, 2026). "Conversely, ADAR2 demonstrates tumor-suppressive activity via editing of transcripts like COPA, switching its function from oncogenic to suppressive by inhibiting PI3K/AKT/mTOR signaling." (PMID 40852728, 2025). "The mechanistic target of rapamycin (mTOR) pathway is now recognised as a critical regulator of immunological responses within the TME, coordinating tumor cell metabolism, immune suppression, and inflammatory signalling." (PMID 40872585, 2025). "NR6A1 activated glycolysis through p-mTOR signaling and the miR-302a/HK1 axis and ultimately promoted tumor cell proliferation." (PMID 41219936, 2025). "Western blot results further supported these findings, revealed that the combined treatment significantly blocked the phosphorylation levels of AKT, mTOR, ERK, and enhanced the expression of cleaved-PARP in tumor tissues." (PMID 41145422, 2025). "The mTOR-mediated cellular metabolism is involved in the interaction of cancer and immune cells with TME during tumor progression." (PMID 40519272, 2025). "The PI3K/mTOR/AKT pathway is frequently aberrantly activated in both subtypes of MCC and research suggests that it has a significant implication in tumor progression." (PMID 40227764, 2025). "We summarize the crosstalk between the UPR and multiple signaling pathways, including mTOR, MAPK, and NF‐κB, which collectively promote tumor growth and metastasis." (PMID 40547943, 2025).
tumor (continued). "Functional experiments demonstrated that knockdown of PGK1 or PCMT1 inhibited tumor cell proliferation and reduced the phosphorylation levels of mTORC, P70S6K, S6, and AKT, indicating suppression of the PI3K/AKT/mTOR pathways." (PMID 40204712, 2025). "Phosphatidylinositol 3-kinase/protein kinase B/mammalian target of rapamycin (PI3K/PTEN/AKT/mTOR) signaling appears dysregulated in HL, as it is in many histologically different tumor types." (PMID 40183103, 2025). "In vivo, Pioglitazone reduced tumor growth in a metastatic PC3 xenograft model, increased phosho AMPKα and decreased phospho mTOR levels." (PMID 40320521, 2025). "PTEN (phosphatase and tensin homologue deleted on chromosome 10) is a tumour suppressor, that negatively regulates the AKT / mTOR signalling pathway." (PMID 40241211, 2025). "In these cancers, the tumor cells overexpress the ERBB2 receptor, resulting in enhanced ligand sensitivity and persistent activation of the MAPK and PI3K/AKT/mTOR pathways." (PMID 41008893, 2025). "Downstream signaling pathways, including the PI3K-Akt-mTOR pathway, the Ras-Raf-MEK-ERK pathway, and the IGF-IR pathway, can become abnormally and persistently activated, enabling tumor cells to evade trastuzumab's effects and develop drug resistance." (PMID 40303296, 2025). "Traditional STS research has primarily focused on identifying recurrent gene mutations, characterizing oncogenic signaling pathways such as PI3K/AKT/mTOR and RAS/MAPK, and exploring immune checkpoint expression and tumor-infiltrating lymphocytes." (PMID 40963867, 2025). "The tumor suppressor genes PTEN and RAS oncogene, often dysregulated in cancer cells, control the effect of ROS on the P13K/Akt/mTOR pathway." (PMID 40377005, 2025). "Our findings demonstrate that YYN-37 induces distinct cell death mechanisms in different tumor cell lines, highlighting the context-dependent nature of PI3K/mTOR pathway modulation." (PMID 41471338, 2025). "Therefore, we proposed that the CCT6A gene may serve as a key target in LUAD by modulating pathways such as PI-3K/AKT/mTOR, thereby affecting immune cell infiltration in the tumor microenvironment (TME) and playing a critical role in NSCLC progression and drug resistance." (PMID 40953006, 2025). "Under hypoxic conditions in glioma, tumor exosome-derived miR-25-3p drives M2 polarization of TAMs by suppressing PHLPP2 and activating the PI3K/AKT/mTOR pathway, accelerating tumor progression." (PMID 41459510, 2025). "In conclusion, polyphenols exert their anti-cancer effects by regulating the dual-axis balance of RAS, effectively inhibiting pro-tumor signaling pathways, including the downstream MAPK, PI3K/mTOR, and Wnt/β-catenin pathways." (PMID 41301459, 2025). "The most recognized anti-tumor mechanism of metformin is its activation of the AMPK signaling pathway, which in turn inhibits the typically upregulated PI3K/AKT/mTOR pathway involved in tumor progression." (PMID 39776799, 2025). "Treated mice showed tumor inhibition comparable to that achieved with sorafenib, and HCC tissues from the miR-199a-treated group exhibited reduced mTOR and PAK4 protein expression." (PMID 41007803, 2025). "By binding to receptors such as CD44 and integrins, SPP1 activates key signaling pathways including PI3K/AKT/mTOR, Slug/Snail, MAPK/NF-κB, and Ras/Raf/ERK, thereby promoting tumor cell proliferation, migration, invasion, adhesion, and EMT." (PMID 41384115, 2025). "Induction of autophagy, inhibition of the Akt-mTOR pathway’s role in glycolysis and cell motility and reduction of the expression levels of VEGF, p-AKT, and PKM2 in tumour tissue." (PMID 40427522, 2025). "This subpopulation exhibited enrichment in oncogenic pathways, such as mTOR and PI3K‐Akt signaling, both of which are known to drive tumor growth, survival, and resistance to therapy." (PMID 40066708, 2025).
tumor (continued). "Combined targeting of the AKT/mTOR and ERK pathways synergistically suppresses tumor growth, underscoring their cooperative pro-tumorigenic roles." (PMID 40729043, 2025). "Key metabolic regulators, such as PI3K/AKT/mTOR and AMPK, were found to regulate the metabolic reprogramming in tumor cells." (PMID 40696413, 2025). "This knowledge gap highlights the need for mechanistic studies to elucidate how cannabinoids restore tumor suppressor signaling and counteract oncogenic PI3K/AKT/mTOR activation." (PMID 41472794, 2025). "Together, the evidence supports a four-layer model—genotype → pathway architecture (mTORC1/2) → expression rewiring → phenotype—yielding three testable hypotheses: shared vs. tumor-specific drivers (H1), non-mutated network contributors (H2), and expression-defined mTOR dependency (H3)." (PMID 41300706, 2025). "A previous study proved that dying cells induced mTOR activation in the neighboring cells by a paracrine mechanism, providing a key step in CRC tumor cell survival and resistance to drugs." (PMID 41034989, 2025). "Mechanistically, the metabolic shift induced by KD inhibits oncogenic pathways such as PI3K/Akt/mTOR and Ras/Raf/MEK/ERK, while simultaneously activating AMPK, reinforcing mTOR inhibition and enhancing metabolic stress in tumor cells." (PMID 40944286, 2025). "HER2-positive tumours show increased angiogenesis due to HER2-mediated activation of the PI3K/AKT and mTOR pathways." (PMID 41463236, 2025). "Additionally, the mTOR signaling pathway serves as a key regulator of macrophage polarization and function Certain chemotherapeutic agents exhibit dual effects by inducing tumor cell death while simultaneously depleting TAMs, thereby enhancing overall anti-tumor efficacy." (PMID 40343509, 2025). "Immune and stromal cells in the TME are not passive bystanders; they actively secrete various factors that “feedback” to tumor cells, sustaining the activation of pro-survival/proliferative pathways like PI3K/Akt/mTOR." (PMID 41208895, 2025). "It inhibits mitochondrial complex I and mTOR signaling, thereby lowering systemic glucose utilization, enhancing CD8+ T cell-mediated tumor clearance, and improving the efficacy of anti-PD-1 immune checkpoint blockade." (PMID 41181123, 2025). "Temsirolimus (an mTOR inhibitor) was used for the initial recurrence of uterine MLA, but the tumor volume increased by 10%." (PMID 41311737, 2025). "As a core downstream effector, mTOR regulates tumor growth and survival through the mTORC1/2 complex and is a key therapeutic target for RCC, with mTOR inhibitors (such as everolimus) already in clinical use." (PMID 41405787, 2025). "Similarly, in an advanced prostate cancer model, Gnetin C (7 mg/kg/bw, i.p.)significantly blocked tumor progression through MTA1/Akt/mTOR signaling, suggesting that Gnetin C could be effective not only in cancer chemoprevention and interception but also as an active therapeutic strategy." (PMID 40077738, 2025). "Upon activation of its toll-like receptor (TLR) by a tumor antigen, DCs quickly switch to aerobic glycolysis with lactate production and FAS via the TRAF6-PI3K-Akt, mTOR, and HIF-1a signaling pathways." (PMID 39796781, 2025). "In the case of metformin, its CSC-suppressive effects appear to be contingent on tumor-specific metabolic states, including glutamine dependency and AMPK‒mTOR pathway activity." (PMID 40759634, 2025). "The combination of baicalein and metformin produced a synergistic anti-tumor effect and more effectively inhibited the AMPK/PI3K/mTOR signaling pathway than either agent alone." (PMID 41303544, 2025). "mTOR, a key downstream target of AKT, serves as a central regulator of multiple tumor cell signaling pathways." (PMID 39873475, 2025).
tumor (continued). "It suppresses tumor proliferation through mechanisms involving the TRPM7 channel and PPM1D phosphatase, while inducing apoptosis via modulation of the AKT/mTOR and Bax pathways." (PMID 41367628, 2025). "SIRT4 depletion promotes HCC tumour development through the AMPKα/mTOR pathway, while overexpression of SIRT4 induces G2/M cell cycle arrest and apoptosis, leading to tumour suppression." (PMID 40136715, 2025). "The PI3K/AKT/mTOR pathway, by regulating cell proliferation and survival, collaborates with the TGF-β/Smad pathway to augment tumor invasiveness." (PMID 40699663, 2025). "Hyperactivation of the PI3K/mTOR pathway enhances DNA-PKcs phosphorylation, accelerating DSB repair and increasing tumor cell resistance to radiation-induced damage." (PMID 40725100, 2025). "Metformin suppresses PKM2 expression and inhibits tumor growth by modulating AMPK and mTOR signaling." (PMID 40735327, 2025). "Although a Phase 2 trial was planned to administer metformin pre-surgery and measure changes in tumor pS6 and other AMPK/mTOR biomarkers, it was withdrawn before completion possibly due to slow accrual." (PMID 41050082, 2025). "This evidence emphasizes the tumor‐suppressive role of miR‐30e‐3p in GC and supports its use as a biomarker and therapeutic agent via modulation of the THOC2/PI3K/AKT/mTOR." (PMID 40740483, 2025). "Single-sample gene set enrichment (ssGSEA) analysis showed the high relevance of KIF15 to tumor proliferation, DNA replication, and the PI3K/Akt/mTOR pathway." (PMID 40087774, 2025). "In a mouse model of AS, combined inhibition of PI3K/Akt/mTOR and MAPK/ERK pathway using rapamycin and trametinib led to sustained tumor regression compared to monotherapy." (PMID 40666093, 2025). "Fasting-mimicking and methionine-restricted diets modulate T-cell fitness and tumor vulnerability via nutrient stress sensors (e.g., UPR, mTOR)." (PMID 40565936, 2025). "ONC201 also downregulated survival pathways (PI3K/AKT/mTOR, MAPK/ERK), reduced Vascular Endothelial Growth Factor Receptor (VEGF) and Snail expression, and suppressed tumor growth in vivo." (PMID 41155556, 2025). "In oral cancer, ANLN activation leads to phosphorylation of PI3K, mTOR, AKT, and PDK-1, resulting in markedly elevated pathway activity that promotes tumor development." (PMID 41573677, 2025). "In mice with tumors of TNBC, PVT significantly reduced tumor growth and the expression levels of PTP1B, CXCL12, CXCR4, PI3K, AKT, mTOR and other proteins in TNBC tumor tissue and upregulated the expression of IL-24." (PMID 40076586, 2025). "Among the drugs circulating on the market, Everolimus, as an anti-tumor drug (DB01590), clearly acts on mTOR." (PMID 40597357, 2025). "The WNT974-artesunate combination efficiently targeted the PI3K/Akt/mTOR axis and promoted KRAS degradation, which is desirable in resistant CRC cases, albeit data on long-term tumor suppression and survival are limited." (PMID 41149466, 2025). "This notion is supported by previous studies demonstrating the crucial role of mTOR in SASP production, and mTOR inhibition suppressing the senescent cells’ ability to promote tumor growth in mice." (PMID 40100482, 2025). "The final approach for characterizing molecular mediators of tumor cell responsiveness based on CS grade was to examine the effects of SMI1182, DOX, and BEZ on insulin/IGF/IRS signaling downstream through mTOR networks using multiplex ELISA platforms." (PMID 40427168, 2025). "For instance, the E3 ubiquitin ligase FBXL6 promotes tumor metastasis through the KRAS/MEK/ERK/mTOR pathway, and this effect is significantly blocked by the mTOR inhibitor everolimus and the MEK inhibitor trametinib." (PMID 41303712, 2025).